IDO1 (indoleamine 2,3-dioxygenase 1)
Diseases named in the same sentence as IDO1 in open-access papers (continued):
Sharing a sentence is not in itself a finding about the gene and the disease.
retinopathy of prematurity (1 paper, 2023). A bilateral retinopathy characterized by neovascularization, scarring, retinal detachment, and eventually blindness. "To begin to explore this possibility, we looked at the impact of IDO1 loss in OIR (oxygen-induced retinopathy), which is a mouse model for ROP (retinopathy of prematurity), a complication that can develop in premature infants receiving neonatal intensive care." (PMID 37182174, 2023).
SARS-CoV infection (1 paper, 2016). "Cxcr3, Ido1, and Ptgs2 were also selected based on prior interest in identifying critical mediators of the immune/inflammatory response not previously known to influence SARS-CoV infection." (PMID 27663205, 2016).
seminoma (1 paper, 2025). A radiosensitive malignant germ cell tumor found in the testis (especially undescended), and extragonadal sites (anterior mediastinum and pineal gland). "This comparison revealed that IDO1 was highly expressed in seminoma, YST, EC, and teratoma compared to controls, suggesting a common role for IDO1 in creating an immunosuppressive environment across both pediatric and adult GCTs." (PMID 40621458, 2025).
shigellosis (1 paper, 2019). Shigellosis is a bacterial infection leading to dysentery and is caused by Shigella, which are small, ubiquitous Gram-negative bacteria belonging to the enterobacteria family. "The perturbation of Wnt signaling compromised IDO1 expression and pharmacological inhibition of IDO1 in mice exacerbated Shigellosis by inducing intestinal hyper-inflammation." (PMID 31497020, 2019).
Skeletal muscle atrophy (1 paper, 2025). The presence of skeletal muscular atrophy (which is also known as amyotrophy). "This study, for the first time, demonstrates that gut microbiota dysbiosis upregulates colonic IDO-1, promotes Trp-Kyn metabolism, and exacerbates burn-induced skeletal muscle atrophy, suggesting that Trp supplementation may be a potential therapeutic strategy." (PMID 39950940, 2025).
skin inflammation (1 paper, 2020). "IMQ treatment induced a psoriasiform skin inflammation in both WT and IDO1 KO mice." (PMID 32752186, 2020). "Therefore, because IDO1 is not expressed or weakly expressed in the epidermis, it might not affect IMQ-induced dermatitis." (PMID 32752186, 2020).
spinal chordoma (1 paper, 2021). A slow-growing malignant bone tumor arising from the remnants of the notochord and occurring in the spine. "Here, we aimed to determine the expression of PD-L1, HHLA2, B7H3, IDO-1 and Galectin-9 in spinal chordoma and evaluated their association with tumor infiltrating lymphocytes (TILs), clinicopathological characteristics and survival of patients." (PMID 35145510, 2021). "The present study objectively measured the tumoral and stromal expression of PD-L1, HHLA2, B7H3, IDO-1 and Galectin-9 in spinal chordoma tissues and analyzed their relationship with the clinical data of patients." (PMID 35145510, 2021). "In this study, we sought to objectively measure the expression of PD-L1, HHLA2, B7H3, IDO-1 and Galectin-9 in spinal chordoma tissues by multiplexed quantitative immunofluorescence (QIF)." (PMID 35145510, 2021). "In this study, we objectively analyzed the expression and coexpression of PD-L1, HHLA2, B7H3, IDO-1 and galectin-9 in spinal chordoma tissues and investigated the clinical impact of these immune checkpoints." (PMID 35145510, 2021).
Staphylococcus infections (1 paper, 2021). "Studies have also shown that iNOS triggered by secreted cytokines in RPE against Staphylococcus infections mediates anti-inflammatory effects that, in turn, prevent IDO-1-dependent tissue damage." (PMID 34869079, 2021).
steatosis (1 paper, 2022). Increased lipid within the cytoplasm of cells. "Additionally, steatosis was observed in the control mice as validated by the massive lipid depositions, while the Ido1-aKO mice were featured by the increased lipolysis (p-HSLSer660) and decreased lipogenesis (p-ACCSer79) coupled with relieved adipocyte hypertrophy in the WAT." (PMID 35715443, 2022).
stress-related disorder (1 paper, 2018). Stress-related disorders are mental health disorders that are a result of an atypical response to both short and long-term anxiety due to physical, mental, or emotional stress. "In addition, altered IDO1 activity and Trp metabolism are involved in many stress-related disorders, and stress-induced cortisol increases IDO1 activity and gut permeability." (PMID 29468141, 2018).
substance abuse (1 paper, 2024). The use of a drug for a reason other than which it was intended or in a manner or in quantities other than directed. "Therefore, this present study is carried out to investigate the association of genetic polymorphisms of IDO1/2, TDO2, and KMO as biomarkers for increased risk of substance abuse in the AoU database." (PMID 39596587, 2024).
ulcer (1 paper, 2019). "The highest expression of IDO-1 was observed at the margin of mucosal erosions and in the reparative ulcer-associated cell lineage suggesting important role of IDO-1 in mucosal healing and regeneration of injured epithelial cells." (PMID 31336879, 2019).
undifferentiated pleomorphic sarcoma (1 paper, 2021). An undifferentiated soft tissue sarcoma characterized by the presence of a pleomorphic malignant cellular infiltrate. "According to a previous study, IDO1 expression could serve as a favorable prognostic biomarker in undifferentiated pleomorphic sarcoma (UPS), which is consistent with our results." (PMID 34733885, 2021).
uterine carcinosarcoma (1 paper, 2020). A usually aggressive malignant neoplasm arising from the uterine corpus and less often the cervix. "We also observed that high IDO1 expression and high TMB had a better clinical outcome than other IDO1/TMB expression patterns in female cancer except uterine carcinosarcoma." (PMID 32227579, 2020).
vascular tumor (1 paper, 2020). "Besides, our study also found that the increased tumor IDO1 expression after neoadjuvant therapy positively correlated with poor pathological response, pN+, poor pathological TNM staging (III/IV), nerve invasion and vascular tumor thrombus." (PMID 32733806, 2020).
viral myocarditis (1 paper, 2023). Myocarditis that is caused by an infection with a viral agent. "Also, IDO1 depletion has been shown to induce an anti-inflammatory response in macrophages from mice with chronic viral myocarditis." (PMID 37081894, 2023).
well-differentiated thyroid cancer (1 paper, 2023). "In papillary thyroid carcinoma (PTC), which is the most common form of well-differentiated thyroid cancer, most checkpoint molecules, including LAG-3, PD-1, ICOS, and IDO1, are significantly reduced compared to TIM-3, whose expression is significantly enriched." (PMID 37567938, 2023).
xanthoma (1 paper, 2022). A non-neoplastic disorder characterized by a localized collection of histiocytes containing lipid. "However, IDO1+ and PD-L1+ cells were nearly absent in all xanthomas and endometrial lesions and rare in foreign body granulomas." (PMID 35058616, 2022).
tumor (1,727 papers, 2008 to 2026). "In HCC, IDO1 overexpression is closely linked to malignant tumor behavior and an immunosuppressive state." (PMID 41293169, 2025). "IDO-1 levels are elevated in the tumor microenvironment and are strongly associated with its malignancy." (PMID 40710094, 2025). "Activated T cells experience cell cycle arrest as a result of elevated IDO1 activity and enhanced Trp depletion, which causes apoptotic T cell death, increases immunosuppression, and reduces the generation of indole in the tumor microenvironment." (PMID 40825672, 2025). "In oral squamous cell carcinoma, increased tumour infiltration of macrophages expressing high levels of IDO1 was also associated with worse prognosis." (PMID 40751253, 2025). "IDO-1 positivity in tumor cells was found to be significantly associated with OS in the univariate setting and in the multivariable model [P-value = 0.009 and 0.021, respectively; HR: 0.72 (95% CI: 0.55-0.95)]." (PMID 40475772, 2025). "IDO1 expression within the tumor microenvironment is linked to both immunostimulatory and immunosuppressive effects that impact DC function." (PMID 40667699, 2025). "Overexpression of IDO1 in tumor cells and stromal immune cells causes tryptophan depletion and KYN accumulation, which suppresses antitumor T-cell responses and promotes regulatory T-cell differentiation." (PMID 40869331, 2025). "IDO-1 positivity in tumor cells was found to be significantly associated with OS in the univariate setting and in the multivariable model where variables including age, sex, histology, stage, EGFR, KRAS and PD-L1 status were included." (PMID 40475772, 2025). "The tryptophan catabolism enzyme IDO-1 has emerged as an intriguing target implicated in tumor immune escape." (PMID 40475772, 2025). "IDO1 is a key enzyme in the tryptophan metabolic pathway, and its high expression in the tumor microenvironment is closely associated with immune evasion." (PMID 40217479, 2025). "High NOS2/COX2-expressing tumors exhibited increased IDO1 clustering that was more closely associated with tumor margins proximal to elevated NOS2Tumor regions, while low expression was observed in immune desert regions in deceased patient tumors." (PMID 40663402, 2025). "Integrated multi-omics analyses have identified IDO1 as a co-expression partner of PD-1 on tumor-associated macrophages, underscoring its utility as both a prognostic biomarker and a promising immunotherapeutic target in ESCC." (PMID 41208974, 2025). "Overexpression of IDO1 in tumor tissues caused tryptophan depletion in the TME, which suppressed T-cell immune function and mediated immune escape from tumors." (PMID 39910672, 2025). "The focus of this previous study, however, was on the immunomodulatory effect of cisplatin in MSCs, specifically the suppression of IL-6 and IDO1 and the associated potential effects on the tumor microenvironment." (PMID 41515960, 2025). "IDO1 plays a significant role in immune evasion mechanisms, which are frequently associated with tumor progression and resistance to therapy." (PMID 40287406, 2025). "During treatment, predominant infiltration of IDO1-expressing tumor-associated macrophages and significantly elevated plasma Kyn/Trp ratio both indicate robust IDO1 pathway activation that likely counteracts PD-1 inhibition efficacy." (PMID 40496774, 2025). "Indoleamine 2,3-dioxygenase 1 (IDO1) is an enzyme that plays a critical role in immune suppression within the tumor microenvironment of HPV-associated cancers." (PMID 40282436, 2025). "FOXM1 from exosomes derived from TNBC can promote cancer progression by activating IDO1 transcription in macrophages to inhibit ferroptosis and induce M2 polarization in tumor-associated macrophages." (PMID 40657248, 2025). "To further test the functional significance of elevated IDO1 expression and tryptophan metabolism in Dock2 deficient tumours we next examined the effect of IDO1 inhibition on tumourigenesis." (PMID 39242821, 2024).
tumor (continued). "The specific microenvironment with massive tumor‐infiltrating lymphocytes caused Trp consumption through IFN‐γ/IDO1 pathway." (PMID 38994917, 2024). "MPO+ neutrophils and CD68+IDO1+ tumor-associated macrophages (TAMs) were enriched in the epithelial compartment, and myeloid lineage cells were located nearest to tumor cells." (PMID 38951801, 2024). "We further validated this upregulation at protein level observing upregulation of IDO1 protein in Dock2 deficient tumours by IHC and Western blot." (PMID 39242821, 2024). "The relationship between IDO1 and marker genes of tumor-associated macrophages (TAMs; CCL5, CD68, and IL10), M1 (IRF5, NOS2, and PTGS2), and M2 (CD163, VSIG4, and MS4A4A) macrophages was analyzed." (PMID 39351094, 2024). "In tumor microenvironment, IDO-1 is highly expressed by dendritic cells, tumor-associated macrophages, myeloid-derived suppressor cells, and cancer-associated fibroblasts, which are all associated with immunosuppressive effects." (PMID 37981615, 2024). "We find this increased tumourigenesis is associated with CD3 + T cell infiltration, increased interferon gamma signalling, elevated expression of the IFNγ target IDO1 and increased tryptophan metabolism in Dock2-deficient tumours." (PMID 39242821, 2024). "Previous studies have demonstrated the immunomodulatory effects of IDO1 on multiple types of immune cells, including tumor-associated DCs, regulatory T cells (Tregs), myeloid-derived suppressor cells (MDSCs), NK cells, and TAMs." (PMID 39351094, 2024). "Meanwhile, siIDO1 silencing of the IDO1 metabolic pathway alleviated immune brakes associated with immunonegative cells, such as Tregs and M2‐TAMs, which further reinforces anti‐tumor immunity." (PMID 38884220, 2024). "Dock2-deficient tumours displayed increased levels of IFNγ-associated genes, including the tryptophan metabolising, immune modulatory enzyme, IDO1, when compared to Dock2-proficient tumours." (PMID 39242821, 2024). "It has been reported that tumor-associated macrophages and dendritic cells (DCs) express high levels of IDO1, leading to local depletion of tryptophan and Kyn overproduction." (PMID 38448800, 2024). "As mentioned, strong correlations were observed between high IDO1 expression and immune checkpoints such as PD-L1, as well as markers related to MDSCs, tumor-associated macrophages, and regulatory T cells." (PMID 38632994, 2024). "Using Human Protein Atlas alongside Tumor-Immune System Interaction Database, we assessed the association of IDO1 with survival rates." (PMID 39312339, 2024). "High IDO-1 expression in tumor endothelial cells in patients with mRCC is associated with better therapeutic response to nivolumab." (PMID 39054430, 2024). "Single-cell RNA sequencing data analysis and multiplexed immunofluorescence verified the coexpression of IDO1 and PD-1 in tumor-associated macrophages (TAMs)." (PMID 39351094, 2024). "This phenotype was driven by increased IFNγ-production in T cell populations, which infiltrated Dock2-deficient tumours, promoting IDO1 expression in tumour epithelial cells." (PMID 39242821, 2024). "An important role for tumor-expressed IDO1 is further corroborated by the effective IDO1 inhibitor-mediated suppression of tumor growth in IDO1-deficient hosts." (PMID 39211039, 2024). "IDO1 is highly expressed in tumor cells and has been linked to prognosis and tumor progression in gastric cancer." (PMID 39227970, 2024). "Next, immune markers related to the tumor immune microenvironment were selected (Resource S1), and the association between their RNA expression and IDO1 RNA expression was analyzed." (PMID 38632994, 2024). "Dual inhibition of IDO1/TDO2 using AT-0174 reduced tumor growth, diminished tumor-associated macrophages (TAMs), and suppressed PD-L1 expression." (PMID 39911818, 2024). "In cancer, IDO1 is overexpressed and has been linked to poor prognosis in several tumor types, including lung, ovarian, and pancreatic cancers." (PMID 39911818, 2024).
tumor (continued). "Another approach to enhance tumor cell susceptibility to the immune system involves targeting indoleamine 2,3-dioxygenase-1 (IDO1) to address the immune-suppressive microenvironment." (PMID 39030582, 2024). "We further dissected the association between IDO1 expression and immunomodulators to better understand the effect of IDO1 expression on tumor immunity." (PMID 39312339, 2024). "IDO1 is expressed in multiple tumor types and is associated with reduced activation of cytotoxic cells, increased infiltration of tumor-regulating T-cells, poorer survival rates, and increased drug resistance." (PMID 37046602, 2023). "Through its capacity to support neovascularization, IDO1 contributes to an inflammatory state that not only is tumor promoting, but also more broadly pathogenic." (PMID 37182174, 2023). "Overexpression of IDO1 is considered an important driver of tumor associated immune suppression and a key to establishing immune tolerance of cancer antigens." (PMID 37114134, 2023). "In various cancers, IDO1 is expressed both in tumor cells and in cancer-associated cells in the tumor microenvironment, including antigen-presenting cells." (PMID 37108483, 2023). "Kaplan Meier survival analysis showed that high expression of IDO1 on tumour cells (score of 2) was associated with better survival in terms of PFS (p = 0.006) and OS (p = 0.034)." (PMID 37527282, 2023). "The main function of IDO1 is to decompose Trp into Kyn and its downstream metabolites, which are responsible for tumor immune escape by regulating T cell-associated immune responses and promoting the activation of immunosuppressive cells." (PMID 37334368, 2023). "One of them, IDO1, is a principal regulator of the tryptophan (Trp) catabolism pathway, leading to the loss of antitumor immunity and tumor growth." (PMID 37958467, 2023). "Currently, an increasing number of studies have demonstrated that IDO1 is associated with immune escape by suppressing T cell activity and enhancing regulatory T cells in different tumor types." (PMID 38168324, 2023). "Collectively, our results show that inhibition of ERO1a and IDO1 modulates the tumor microenvironment associated with improved monocyte infiltration and differentiation into dendritic cells to potentially influence therapeutic responses in patients with PDAC." (PMID 38187398, 2023). "The signaling pathways associated with IDO1 catalytic activity play critical roles in tumor development, metastasis, and prognosis." (PMID 36831659, 2023). "IDO1 expression is found not only in tumor cells but also in immune cells and is associated with tumor proliferation and immune responses." (PMID 36653774, 2023). "IDO1 depletes tryptophan, with deficiencies in this essential amino acid leading to suppression of immune response to tumours." (PMID 37446864, 2023). "RIME‐MLL1 epigenetically upregulated the expression of immunosuppressive molecules PD‐L1/IDO‐1 in tumour cells and caused T‐cell dysfunction and immune evasion by promoting the accumulation of H3K4me3 in their promoter regions." (PMID 37712124, 2023). "There is a broadly similar tissue distribution in IDO1 and PD-1, with parallel changes in disease stage or treatment and with significant associations between them in the tumor microenvironment." (PMID 37296860, 2023). "Many studies have shown that IDO1 is highly expressed in various cancers and is associated with tumor aggressiveness and poor prognosis." (PMID 37503314, 2023). "In MB, a mutated mTOR pathway leads to increased IDO1 expression, which triggers the expansion of regulatory T cells enabling tumor cells to grow." (PMID 37509316, 2023). "Nevertheless, studies using BALB/c nude and K14.E7 (expressing E7 HPV gene) mice models in vivo showed that the downregulation of IDO1 was significantly associated with an increased number of infiltrating NK cells and decreased tumor growth." (PMID 36831674, 2023).